IL1B (interleukin 1 beta)
Diseases named in the same sentence as IL1B in open-access papers (continued):
Sharing a sentence is not in itself a finding about the gene and the disease.
diabetes (continued). "Systemic and local inflammation (TNFα, IL-1β, CD68) were increased with diabetes." (PMID 32153425, 2020). "At a minimum, caspase-1-mediated IL-1β production is not indispensable for diabetes development in NOD mice." (PMID 32973739, 2020). "Ablation of neuronal Pdk2 in the hypothalamus did not alter diabetes-induced expression levels of Tnf-α, Il-1β, and Il-6 mRNA, or gliosis." (PMID 33219201, 2020). "In this study, we showed that STZ-induced diabetes resulted in DR, and 12 weeks of LTF treatment ameliorated retinal damage, delayed DR occurrence, and significantly decreased the expression of TNF-α, IL-1β, MCP-1, and ICAM-1." (PMID 31956338, 2020). "Furthermore, in a mouse model of diabetes, the treatment with mangiferin reduced IL-6, TNF-α, and Il-1β expression by inhibiting PTEN/PI3K/Akt pathway." (PMID 32471207, 2020). "Moreover, diabetes mellitus leads to increased expression of proinflammatory cytokines, such as TNF-α and IL-1β, and increased inflammation is also considered to be involved in the pathogenesis of depressive symptoms in type 2 diabetes mellitus." (PMID 31681052, 2019). "Plasma aldosterone levels—augmented in diabetic and hypertension patients and experimental models of diabetes—contribute to the increased expression of inflammatory markers, such as TNF-α, chemotactic protein macrophage, transforming growth factor-beta and IL-1β." (PMID 31817997, 2019). "Despite the observed modifications of IκBα, diabetes induction and dietary fortifications did not change mRNA expression of the pro-inflammatory interleukins targeted in the study (IL-1β, 6, and 10)." (PMID 31690052, 2019). "Neither maternal diabetes nor LPS (1 μg/ml, 24 h) had any effect on the protein level of IL-1β in the homogenates." (PMID 31197747, 2019). "Interestingly, with ANOVA analysis, the exercise significantly increased circulating inflammatory markers (IL-1β, IL-6, TNF-α, and IL-10) and decreased WBC, while diabetes displayed significant effect on HR and TNF-α." (PMID 29467719, 2018). "Macrophages, by the release of proinflammatory cytokines (e.g., TNF-α, IL-6, and IL-1β), aggravate inflammation, which may be explained by the increased GLU activity in the STZ-induced diabetes." (PMID 29464184, 2017). "Intravitreal injections of anti-Il-1β and anti-Tlr4 neutralizing antibodies to animals with STZ-induced diabetes significantly reduced retinal Lgals1 expression (anti-Il-1β, fold change = 1.96; anti-Tlr4, fold change = 1.41) compared to normal IgG treatment (fold change = 3.55)." (PMID 29170525, 2017). "Animal studies showed that prolonged healing of peptic ulcer in diabetic rats was associated with increased gastric mucosal expression and release of TNF-α and IL-1β, evidenced that amplification of local inflammation is also responsible for delayed healing process of PUD in diabetes." (PMID 29095895, 2017). "Moreover, the anti-inflammatory action of melatonin was demonstrated by a significant decrease in cytokines IL-1β, IL-6 and PGE2 in gingival crevicular fluid of patients with diabetes and periodontal disease." (PMID 29075409, 2017). "In particular, in diabetes, mitochondrial DNA, a by-product of insufficient mitophagy, induced sterile inflammation and subsequent cardiac dysfunction through the TLR9 pathway, and increasing IL-1β, IL-6, and infiltration of CD68+ macrophages." (PMID 28659798, 2017). "In summary, diabetes-induced generation and accumulation of AGE were suggested to activate IL-1β-related inflammatory cues in monocyte-derived macrophages/microglia followed by Müller glia, linking to the upregulation of galectin-1 along with the severity of DR." (PMID 29170525, 2017). "The mechanism for this diabetes-induced brain immune alteration is unclear, but it appears that diabetes has an effect on the IL-1β counterregulation, as IL-1Ra did not increase after LPS administration in diabetic mice." (PMID 28109186, 2017).
diabetes (continued). "L-NAME but not D-NAME supplementation markedly decreased diabetes-induced IL-1β and TNF-α mRNA expression of Kupffer cells in STZ-DM mice." (PMID 28493939, 2017). "While the deleterious role of IL-1β in renal cells during diabetes is not clearly established, IL-18 deleterious role is clearly demonstrated." (PMID 29359167, 2017). "However, one month later western blotting analysis showed an increase in the amount of immunoreactive peptide for IL-1β, IL-6, and TGF-β1 in plasma of groups with diabetes (resp)." (PMID 26955430, 2016). "Diabetes did not induce changes neither in inflammatory cytokines (IL-1β and IL-6) nor in the profibrotic cytokine TGF-β1 at short term (1 week) (data not shown)." (PMID 26955430, 2016). "Silymarin administration in experimental diabetes induced in mice reduced levels of inflammatory cytokines (TNF-α and IL-1β) and oxidative stress mediators like myeloperoxidase activity, lipid peroxidation, carbonyl, and thiol content of pancreatic tissue in an almost dose-dependent manner." (PMID 27340676, 2016). "We demonstrated that increased levels of pro-inflammatory cytokines, IL-1β and TNF-α were secreted by BM-derived DC and splenocytes derived from diabetic mice, indicating that diabetes may lead to aberrant activation of BM and splenic derived immune cells." (PMID 26760976, 2016). "No changes in plasma levels of OPN, IL-10, TNFα, IL-12p70, IL-1β, IL-6, and KC were observed in response to diabetes or NFAT inhibition; however plasma IFN-γ was reduced in diabetic animals that had been treated with A-285222." (PMID 25918731, 2015). "Glucose level, LVWI, TGF-β1 and IL-1β level, and collagen volume fraction were significantly reduced in diabetic rats treated by PCA in a dose-dependent manner (P < 0.050), especially in the high dose (8 mg/kg) group (P < 0.010), compared to diabetes group." (PMID 26526881, 2015). "The ischemia-induced upregulation of those cytokines was markedly accelerated by diabetes: the diabetic control group showed a 15.9- and 21.0-fold increase in IL-1β and TNF-α expression, respectively, compared with the nondiabetic control group." (PMID 24739976, 2014). "The present study evaluates the effects of extract of Musa sapientum fruit (MSE) on ulcer index, blood glucose level and gastric mucosal cytokines, TNF-α and IL-1β and growth factor, TGF-α (affected in diabetes and chronic ulcer) in acetic acid (AA)-induced gastric ulcer (GU) in diabetic (DR) rat." (PMID 24192345, 2013). "Prolonged production of IL-1β and MIP2, induction of ER stress, and increased apoptosis might contribute to K. pneumoniae-related hepatic damage in mice with diabetes." (PMID 24223208, 2013). "We first found that diabetes induction was accompanied by an elevation in the plasma levels of reactive oxygen species (ROS), hydroperoxide, malondialdehyde (MDN), and the proinflammatory cytokines IL-1α, IL-1β, IL-6, and CXCL10." (PMID 23533683, 2013). "Various studies have demonstrated that inhibition of pro-inflammatory cytokines (such as IL-1β, TNF-α, and VEGF), chemokines (such as MCP-1), or adhesion molecules (such as ICAM-1) can reduce diabetes-induced leukostasis, degeneration of retinal capillaries, or BRB breakdown." (PMID 23662142, 2013). "Thus, WP supplementationduring diabetes significantly restored the levels of TNF-α, IL-1β,IL-6 and IL-10." (PMID 22708778, 2012). "In addition, supplementation with α-tocopherol resulted in decreased circulating IL-1β, IL-6, TNF-α, and CRP in individuals with diabetes." (PMID 23158971, 2012). "Further, lack of TNFα prevented the up-regulation of IL-6 and IL-1β mRNA otherwise observed in wt mice in response to diabetes." (PMID 20856927, 2010). "Similar beneficial effects of curcumin supplementation were obtained on diabetes-induced increased protein expression of retinal IL-1β, p65 subunit of NF-kB and VEGF (data not shown)." (PMID 17437639, 2007).
diabetes (continued). "CGA has been shown to modulate the production of inflammatory mediators such as TNF-α, IL-1β, IL-6, IL-8, NO, and PGE2, and regulate key signaling pathways such as NF-κB, MAPK, and Nrf2, providing protective effects against cardiovascular disease and diabetes mellitus." (PMID 40943313, 2025). "Inhibited EGFR/PI3K/AKT signaling pathway, reduced the released of inflammatory factors IL-1β, IL-6, TNF-αImproved lipid and glucose metabolism, promoted adipogenesis, improved insulin sensitivity by regulating PI3K-Akt signaling pathway, and fight against diabetes and its complications." (PMID 41356003, 2025). "Additionally, downregulation of PDK4 curbed the protein expression of β‐MyHc, IL‐1β, and cleaved caspase‐3 in HG/HP‐incubated cardiomyocytes, suggesting that PDK4 may be a driver for diabetes‐induced cardiac hypertrophy, apoptosis and oxidative damage." (PMID 40052435, 2025). "Studies from the field of Diabetes Mellitus (DM) directly link NLRP3 and CGRP-related pathways, where NLRP3 activation (e.g., via reactive oxygen species) and consequent IL-1β production have been shown to affect receptor resistance and apoptosis in DM models." (PMID 39568667, 2024). "IL-1β, IL-6 and TFN-α are particularly relevant, contributing to cancer and the majority of inflammatory disorders, including cardiovascular disorders, rheumatoid arthritis and several other autoimmune inflammatory diseases, pulmonary inflammation, as well as type-2 diabetes mellitus." (PMID 38581641, 2024). "In addition, we investigated IL1β expression and identified a significant increase in IL1β staining intensity in the retinal fiber layer with diabetes, which was not present in PTX3KO mice." (PMID 39348530, 2024). "Under high glucose and oxidative stress conditions, like those observed in diabetes, SCs express increased levels of nuclear factor-κβ (NF-κβ), Toll-like receptors (e.g., TLR4) and pro-inflammatory cytokines and chemokines such as TNF-α, IL-6, IL-1β, CXCL9, CXCL10, and CXCL11." (PMID 38236305, 2024). "The activity of inflammatory cytokines such as interleukin-1 beta (IL-1β) and tumor necrotic factor-alpha (TNF-α) as well as the pro-inflammatory transcription factor, nuclear factor kappa B (NFκB), has been found to be significantly increased in diabetic retina." (PMID 37268913, 2023). "To determine whether IL-36R signaling also modulates IL-1β and IL-1Ra expression, we assessed their expression levels in WT and IL-36R−/− mice with or without diabetes." (PMID 37371057, 2023). "In diabetes, excessive FTO downregulates TNIP1, a central regulator of inflammation, thereby activating NF-κB and subsequently increasing inflammatory cytokines (IL-1β and IL-18) in an m6A-dependent manner, ultimately leading to vascular endothelial dysfunction." (PMID 37781923, 2023). "This led to the proposal that targeting the IL-1β-pathway may reduce diabetes complications rather than prevent its incidence." (PMID 37914804, 2023). "Meanwhile, the elevated level of IL-1β further confirmed that ER-stress-related inflammatory pathways were activated by PA exposure, which was consistent with the reported studies describing the inflammatory NLRP3 pathway that interacts with ER stress pathways in diabetes." (PMID 35565803, 2022). "Diabetes increased TLR4-mediated inflammation, whereas DP inhibited the protein expression of the TLR4 pathway (TLR4, Myd88, IRAK1, and TRAF6) and reduced the mRNA expressions of IL-1β, IL-1α, IL-6, and TNF-α and the protein expressions of TNF-α, IL-1β, and COX-2." (PMID 35463063, 2022). "In addition, the injection of nondiabetic plasma-treated SVFs not only repressed the expression of the diabetes-induced ICAM, FMO3, IL-6, IL-1β, iNOS, TNF-α, and DPP4 expression, but also suppressed the phosphorylation of JNK and NF-κB in the liver of diabetic mice." (PMID 35883204, 2022). "Moreover, IL-1β inhibition with canakinumab did not reduce incident diabetes among CANTOS participants over a median period of 3.7 years." (PMID 35629988, 2022).
diabetes (continued). "Also, the relationship between age and IL-1β, IL-6, or TNFα production was not seen in this population compared to the healthy subjects, arguing that the presence of diabetes supersedes the impact of age." (PMID 36337734, 2022). "In cases of systemic inflammation, such as obesity-induced diabetes, pro-inflammatory cytokines can be present in the blood and concentrated in fat tissues as activated adipose tissue macrophages (ATMs) produce tumor necrosis factor-alpha (TNF-α) and interleukin-1β (IL-1β)." (PMID 34489979, 2021). "In one study, including T1D with T2D subjects with periodontitis, it was found that the GCF levels of IL‐1β and TNF‐α were significantly higher in the T1D subjects as compared to the T2D subjects and these levels were negatively affected by the duration of the diabetes." (PMID 33369174, 2021). "Activation of the diabetes-mediated pyroptosis-related inflammasomes, such as nucleotide-binding oligomerization domain-like receptor protein 3 (NLRP3), Toll-like receptor 4 (TLR4), caspase-1, interleukin (IL)-1β, and the IL-18 axis, plays an essential role in DKD lesions." (PMID 33692782, 2021). "Together, these results suggest the relevance of autophagy in preventing exacerbated inflammation in renal IR-induced AKI, highlighting the contribution of early diabetes to enhancing IL-1β gene expression compared to that observed in nondiabetic mice subjected to renal IR." (PMID 34561469, 2021). "Increased proinflammatory cytokines such as interleukin-1β (IL-1β) and interleukin-6 (IL-6), promote BRB breakdown and increase microvascular impairment, which contribute to the increase of vascular permeability by different signaling pathways in diabetes-induced retinal pathology 12-14." (PMID 32210708, 2020). "The results showed that protein secretion of IL-1β, IL-6 and MCP1 in the STZ/STZ-CTL group increased to 197%, 184%, and 151%, respectively, compared to the CTL/CTL-HSC group, and STZ/CTL-HSC group completely reversed, while the CTL/STZ-HSC group mimicked, the maternal diabetes-induced effect." (PMID 33101089, 2020). "Although IL-1β inhibition with canakinumab had similar effects on major cardiovascular events among those with and without diabetes, treatment over a median period of 3.7 years did not reduce incident diabetes." (PMID 31182982, 2019). "Similarly, given the relevance of inflammatory mediators, and particularly IL-1β, in the pathophysiology of diabetes and diabetic cardiomyopathy, targeting the NLRP3/IL1β pathway could effectively reduce the burden of this disease." (PMID 31652822, 2019). "Finally, liposomal formulation of citicoline was able to ameliorate the overexpression TNF-α, but not of IL-1β, induced by diabetes." (PMID 30127248, 2018). "Reversal of diabetes-induced enteric dysbiosis by prebiotic (FOS) or probiotic (dead L. plantarum) treatment decreased diabetes-induced pJNK and iNOS expression in the intestine, Fmo3 expression in the liver, IL-1β expression in Kupffer cells, and ICAM expression in the aorta and liver." (PMID 29851956, 2018). "Our data suggested that SXT could suppress the activation of IKKβ/NF-κB signal pathway in liver and decrease the CRP, TNF-α, IL-6, and IL-1β levels in serum of T2DM rats, which were corresponding with the results that insulin resistance was markedly ameliorated in SXT-treated diabetes rats." (PMID 30210342, 2018). "In summary, treatment of mouse models of diabetes with IL-1β- and TNF-antagonists, and with sodium salicylate improved insulin secretion and glycaemia to comparable levels, with an additive effect on insulin secretion with the combination of IL-1β- and TNFα-antagonists." (PMID 28740254, 2017). "Diabetes induced a significant increase of IL-1β and TNF-α expression of Kupffer cells in STZ-DM mice as compared with the control group." (PMID 28493939, 2017). "Similarly, IL-1β, iNOS and COX-2 can be up-regulated in the retina with diabetes." (PMID 27973425, 2016).
diabetes (continued). "However, despite an ample amount of preclinical and clinical studies a defined mechanism of action for IL-1β antagonism in diabetes is still lacking." (PMID 26953152, 2016). "Additionally, prior studies using in vivo models of autoimmune-mediated β-cell death (e.g., NOD mice with cyclophosphamide accelerated diabetes) found lack of caspase-3 activation in β-cells, despite the presence of IL-1β." (PMID 21829464, 2011). "Direct experimental evidence in mice models of diabetes is limited, with a study demonstrating elevation of TNFα mRNA in male C57Bl6 mice 5 months after induction of diabetes by STZ and another study showing activation of caspase-1/IL-1β signaling in retinas of diabetic mice." (PMID 20856927, 2010). "However, IL-1β inhibition did not reduce the rates of new-onset diabetes." (PMID 39496966, 2025). "However, no anti-IL-1β antibody-based treatment for diabetes has yet been approved." (PMID 39120275, 2024). "Variables examined not affecting IL-1β expression include antibiotics, piezoelectric osteotomy technique, photobiomodulation, insertion torque, healing abutment type, ridge reduction at time of surgery, pulsed electromagnetic field application, photodynamic stimulation, and diabetes." (PMID 39685706, 2024). "However, to date, no treatment for diabetes with anti-IL-1β antibodies has been approved." (PMID 37008937, 2023). "TNF-α and IL-1β have often been mentioned as playing a key role in both type 1 and type 2 diabetes, and IFNγ is another proinflammatory factor that is critical to the pathogenesis of both types of diabetes, but has not been extensively studied in diabetic retinopathy." (PMID 37670018, 2023). "In addition, expression levels of IL-1β and TNF-α in the endplate were assessed, and it was found that levels of IL-1β (control vs diabetes: 8.158 vs 15.13; p < 0.0001) and TNF-α (control vs diabetes: 104.6 vs 131.7; p < 0.0001) in the diabetic group were increased to various degrees." (PMID 36816302, 2023). "Furthermore, co-culture with exenatide reduced the levels of IL-1β, IL-2, IL-17 and IFN-γ in human islet supernatants, disclosing that Th17 cell may be involved in GLP-1 related immuno-inflammatory modulation under diabetes context as well." (PMID 36463128, 2022). "Similarly, renal gene expression of Il1β, Il18 and Ccl2 as well as glomerular accumulation of CD68-positive cells, which is a macrophage marker, were increased in the MCC950-treated diabetic animals, consistent with MCC950 promoting renal inflammation in diabetes." (PMID 35048962, 2022). "Notably, among current diabetes treatment options used in our study; 10 mg/kg CurNPs and 50 mg/kg ZnONPs exhibited more anti-inflammatory power and showed significant suppression of expression levels of TNF-α, IL-1β as well as iNOS concentration in liver and pancreas." (PMID 34667196, 2021). "However, glucose-induced IL-1β production and NF-κB activation are unlikely to be the main mediators of β-cell glucotoxicity, and transient hyperglycemia is unlikely to be sufficient to trigger the transition from obesity to diabetes." (PMID 33546399, 2021). "Research shows that in diabetes, the abnormally differentiated vascular endothelia cells and perivascular macrophages may show an exaggerated inflammatory response characterized by an in-creased secretion of pro-inflammatory cytokines, such as TNF-α, IL-1β and iNOS." (PMID 33918576, 2021). "Diabetes significantly induced IL-1β and TNF-α expression of the Kupffer cells in STZ-DM mice." (PMID 28493939, 2017). "Here we show that LPS stimulation leads to increased secretion of pro-inflammatory cytokines such as IL-1β and TNF-α by splenocytes and BM-derived dendritic cells enriched from diabetic mice, indicating that these immune cells may also contribute to inflammation in diabetes." (PMID 26760976, 2016).